ENTHD1 (ENTH domain containing 1)
Synonyms: FLJ25421; dJ370M22.3
Tractability: Antibody: its Gene Ontology location is reachable by antibodies, with medium confidence. PROTAC: ubiquitination databases record sites on it.
Gene: Protein-coding gene on chromosome 22 (39,743,044 to 39,893,864, reverse strand). Ensembl gene ENSG00000176177.
Gene Ontology:
Molecular function: protein binding; phospholipid binding
Biological process: endocytosis
Cellular component: clathrin vesicle coat; cytoplasm
Genetic constraint (gnomAD): Loss-of-function variants: 22 observed, 33.87 expected, observed/expected ratio (o/e) 0.65, 90% interval 0.46 to 0.93. The upper end of that interval is the gene's LOEUF score, 0.93, which puts it in group 3 of 6, group 1 being the genes least tolerant of losing a copy. Missense variants: 591 observed, 684.11 expected, observed/expected ratio (o/e) 0.86, 90% interval 0.81 to 0.93. Synonymous variants: 217 observed, 253.01 expected, observed/expected ratio (o/e) 0.86, 90% interval 0.77 to 0.96.
Homologues: Orthologues: chimpanzee ENTHD1 (99% identical), macaque ENTHD1 (93% identical), dog ENTHD1 (71% identical), guinea pig ENTHD1 (65% identical), pig ENTHD1 (61% identical), rabbit ENTHD1 (57% identical), rat Enthd1 (56% identical), mouse Enthd1 (56% identical), Drosophila melanogaster lqf (25% identical), Caenorhabditis elegans epn-1 (21% identical). Paralogues in human: EPN2 (25% identical), EPN3 (25% identical), EPN1 (23% identical), CLINT1 (17% identical), MYCBPAP (11% identical).
Diseases named in the same sentence as ENTHD1 in open-access papers:
ENTHD1 is named in the same sentence as 4 diseases in open-access papers, as found by Europe PMC text mining. Sharing a sentence is not in itself a finding about the gene and the disease. The quoted sentences say what the papers report.
breast carcinoma (2 papers, 2015 to 2018). "In summary, we discovered novel somatic mutations in the TRPM6, HYDIN, ENTHD1 and NDUFB10 genes in early onset Chinese breast cancer patients through whole exome sequencing." (PMID 26870154, 2015). "However, in the previously two exome sequencing studies of breast cancer, no ENTHD1 mutations were observed." (PMID 26870154, 2015).
ischemic stroke (1 paper, 2015). A stroke disorder caused by obstruction of blood flow to the brain, due to thrombotic (local blood clot formation) or embolic (due to a blood clot or other material traveling from another site) event. "Among the downregulated genes, Gpr88, Rgs9, Enthd1, Olr59, P2ry12, Degs2, Pde10a, Neu2, Adora2a, and Slc22a6 were found to demonstrate significant downregulation in pathological phase of ischemic stroke." (PMID 25861363, 2015).
tumor (2 papers, 2015 to 2024). "Within the validated mutations, somatic mutations in the TRPM6, HYDIN, ENTHD1, and NDUFB10 genes were found in two or more tumor samples in the replication stage." (PMID 26870154, 2015). "In this research, the ERGS was composed of 8 ERGs (CXCL9, CYP17A1, DRGX, ENTHD1, HAS1, LAIR2, RETN, and SPHKAP), some of which were pivotal to the tumor progression." (PMID 38600248, 2024).
cancer (1 paper, 2018). A tumor composed of atypical neoplastic, often pleomorphic cells that invade other tissues. "In contrast, some of the genes, including ENTHD1, HELZ2, PCDH12, CPNE4, and SHANK1, that are mutated in metastatic ACCs alone are completely novel and have not been functionally characterized in any cancer type until now." (PMID 30301885, 2018).